RTEL1 (regulator of telomere elongation helicase 1)
Diseases named in the same sentence as RTEL1 in open-access papers (continued):
Sharing a sentence is not in itself a finding about the gene and the disease.
Stroke (4 papers, 2017 to 2024). Sudden impairment of blood flow to a part of the brain due to occlusion or rupture of an artery to the brain. "Our findings reveal a possible association between SNPs in the RTEL1 gene and stroke risk in Chinese population." (PMID 29383136, 2017). "Based on our experimental results, we conclude that perhaps the SNPs in the RTEL1 gene can cause cell apoptosis by influencing the length of telomere, and then causes endothelial dysfunction, and finally affects stroke." (PMID 29383136, 2017). "In this study, we investigated the associations between SNPs in the RTEL1 gene and stroke risk in the Chinese population." (PMID 29383136, 2017). "Additionally, it has also been found that genetic variations of the RTEL1 gene are linked to an elevated risk of stroke." (PMID 39240887, 2024). "For instance, there is a possible association between variants in the RTEL1 gene and stroke risk in the Chinese population while CD320 (transcobalamin 2 receptor) is known to be associated with hyperhomocysteinemia, which is a risk factor for cardiovascular disease." (PMID 37098010, 2023). "In this case-control study, we genotyped five SNPs in RTEL1 gene: rs6089953, rs6010620, rs6010621, rs4809324 and rs2297441, and performed a comprehensive association analysis to identify SNPs associated with the risk of stroke in Chinese population." (PMID 29383136, 2017). "However, so far, no studies have investigated the association between SNPs in the RTEL1 gene and the risk of stroke." (PMID 29383136, 2017). "In summary, we have identified four new associations between the SNPs (Rs6089953, Rs6010620, Rs6010621 and Rs2297441) in RTEL1 gene and stroke." (PMID 29383136, 2017). "We investigated the associations between single nucleotide polymorphisms (SNPs) in the regulator of telomere elongation helicase 1 (RTEL1) gene and stroke in the Chinese population." (PMID 29383136, 2017). "The exact mechanism for explaining the relationship between the SNPs in the RTEL1 gene and stroke cannot be determined from our study alone, we should do further functional experiments to verify." (PMID 29383136, 2017). "Because in previous studies there was a lack of research and reporting on the association between the SNPs in the RTEL1 gene and Stroke, we have no way to compare with other data." (PMID 29383136, 2017).
Fanconi anemia (3 papers, 2017 to 2023). Fanconi anemia (FA) is a hereditary DNA repair disorder characterized by progressive pancytopenia with bone marrow failure, variable congenital malformations and predisposition to develop hematological or solid tumors. "The spontaneous G2 phase accumulation and chromosomal aberrations, and pronounced MMC-induced G2 phase arrest of RTEL1-deficient fibroblasts resemble the phenotype of Fanconi anemia fibroblasts of most subtypes." (PMID 28507545, 2017). "The XPD helicase family comprises XPD and several related super-family 2 DNA helicases including DDX11/ChlR1 (DEAD/DEAH box helicase 11), RTEL1 (regulator of telomere elongation 1), and FANCJ (Fanconi anemia complementation group J)." (PMID 34660592, 2021).
gastric cancer (3 papers, 2016 to 2023). A primary or metastatic malignant neoplasm involving the stomach. "aCGH is a very useful tool for investigating novel genes associated with carcinogenesis and RTEL1 amplification may be important for the development of gastric cancer in older patients, besides being a probable event contributing for chromosomal instability in intestinal gastric carcinogenesis." (PMID 27366209, 2016). "The region 20q, where RTEL1 gene is located, is amplified in several types of cancer, but we were the first group to describe RTEL1 amplification in gastric cancer." (PMID 27366209, 2016). "Thus, RTEL1 amplification may be important for the development of gastric cancer in older patients, besides being a probable event contributing for chromosomal instability in intestinal gastric carcinogenesis." (PMID 27366209, 2016). "In a previous study, performed by array-Comparative Genomic Hybridization, we described for the first time in literature recurrent amplification of RTEL1 and ABCA13 genes in gastric cancer." (PMID 27366209, 2016). "Lastly, RTEL1 and ABCA13 synergistic effect may be considered as a putative marker for advanced staging in gastric cancer patients." (PMID 27366209, 2016).
hepatocellular carcinoma (3 papers, 2016 to 2024). A malignant tumor that arises from hepatocytes. "Interestingly, Ubiquitous overexpression of RTEL1 in the mouse specifically caused hepatocellular tumors that recapitulated a variety of malignant features of human hepatocellular carcinoma (HCC)." (PMID 38532312, 2024). "Interestingly, some other researchers demonstrated that more than 70% transgenic mice that widely overexpress RTEL1 developed liver tumors that recapitulate many malignant features of human hepatocellular carcinoma (HCC)." (PMID 38532312, 2024). "Six genes carrying DNVs were associated with human developmental disorders involving epithelial, connective or bone morphologies (PXDN, RTEL1, ANKRD11, MAP2K1, CYLD, ACAN) and four linked with cholangio- and hepatocellular carcinomas (PIK3CA, TLN1 CYLD, MAP2K1)." (PMID 27955658, 2016).
interstitial lung disease (3 papers, 2018 to 2023). A diverse group of lung diseases that affect the lung parenchyma. "RTEL1 deficiency has also been implicated in the etiology of connective tissue disease‐associated interstitial lung disease (ILD) with rapid progression." (PMID 36253342, 2023). "Mutations in a number of telomere-related genes, including TINIF2, nuclear assembly factor 1 (NAF1), dyskerin pseudouridine synthase 1 (DKC1) and regulator of telomere elongation helicase 1 (RTEL1), have been identified and associated with IPF and other interstitial lung diseases (ILDs)." (PMID 33865386, 2021).
lung adenocarcinoma (3 papers, 2014 to 2023). A carcinoma that arises from the lung and is characterized by the presence of malignant glandular epithelial cells. "More recently, large-scale association analysis identifies sentinel variants associated with lung adenocarcinoma are located near genes related to telomere regulation including RTEL1 rs4130993118." (PMID 31762827, 2019). "For instance, while the RTEL1 locus (20q13.33: rs117238689, rs115610405, rs35640778, and rs35902944) harboured variants associated with both LTL and lung adenocarcinoma, these signals appeared to be distinct and independent of each other (avg_PP3=0.999, avg_PP4=0.001)." (PMID 37079368, 2023). "For example, a chromosome 20q cluster comprising four genes (PTK6, SRMS, RTEL1, and PRPF6) were all amplified in uterine/endometrial cancers and lung adenocarcinomas." (PMID 24874471, 2014).
lymphoma (3 papers, 2018 to 2023). A malignant (clonal) proliferation of B- lymphocytes or T- lymphocytes which involves the lymph nodes, bone marrow and/or extranodal sites. "At an organism level, RTEL1-PIP box knockin mice are viable, but aging studies of these mice revealed that RTEL1 acts as a tumor suppressor and is associated with heighted predisposition to lymphoma and medulloblastoma." (PMID 33357438, 2020).
medulloblastoma (3 papers, 2019 to 2024). A malignant, invasive embryonal neoplasm arising from the cerebellum.
melanoma (3 papers, 2012 to 2016). A malignant, usually aggressive tumor composed of atypical, neoplastic melanocytes. "Similar to the SNP-based findings, the RECQL4 region had the strongest association with the risk of melanoma (gene-based P-value = 2.5×10−3) and the RTEL1 region had the strongest association with risk of dysplastic nevi (gene-based P-value = 0.004)." (PMID 23300679, 2012). "The telomere-associated SNPs in TERC, TERT, OBFC1, and RTEL1 are near (8-150kb from) SNPs strongly associated with melanoma risk (rs12696304 in TERC, P = .0001; rs455433 in TERT, P = 2.26x10-16; rs2995264 in OBFC1, P = 7.10x10-6; rs75691080 in RTEL1, P = 1.02x10-6) (available online)." (PMID 25231748, 2014). "The gene regions around RECQL4, RTEL1 and TERF2 were associated with melanoma, the presence of dysplastic nevi and number of nevi, respectively, in the Italian combined study." (PMID 23300679, 2012).
neuroblastoma (3 papers, 2023 to 2024). Neuroblastoma (NB) is the most common solid, extracranial childhood tumor. "Consistent with the vital role of RTEL1 in malignancies, we report for the first time the association between RTEL1 polymorphisms and the risk of neuroblastoma." (PMID 38001404, 2023). "To determine the association between neuroblastoma susceptibility and RTEL1 gene SNPs, we conducted this case-control study in Chinese children." (PMID 38001404, 2023). "We conducted a study on 402 neuroblastoma cases and 473 controls to assess the association between four RTEL1 SNPs (rs3761124 T>C, rs3848672 T>C, rs3208008 A>C and rs2297441 G>A) and neuroblastoma susceptibility." (PMID 38001404, 2023). "This research investigated the association between four RTEL1 gene SNPs and neuroblastoma risk by conducting a case–control study with 402 neuroblastoma patients and 473 healthy controls." (PMID 38001404, 2023). "In conclusion, we provide the first evidence that polymorphisms rs3848672 T>C and rs2297441 G>A in the RTEL1 gene are associated with the risk of neuroblastoma in the Chinese population." (PMID 38001404, 2023). "Our study indicated that the rs3848672 CC and rs2297441 AA genotypes of the RTEL1 gene are significantly associated with an increased risk of neuroblastoma in Chinese children in a gender- and site-specific manner." (PMID 38001404, 2023). "Single nucleotide polymorphisms (SNPs) in the RTEL1 gene have been reported to confer susceptibility to multiple cancers, but their contributing roles in neuroblastoma remain unclear." (PMID 38001404, 2023). "However, no publication has reported a linkage between RTEL1 gene polymorphisms and the risk of neuroblastoma." (PMID 38001404, 2023).
pulmonary disease (3 papers, 2017 to 2023). "Telomere length, RTEL1 and TERT expression may serve as potential biomarkers related to silica exposure and may offer insight into the molecular mechanism of silica-induced lung disease and tumorigeneses." (PMID 29230030, 2017).
telomere syndrome (3 papers, 2016 to 2023). Accelerated aging syndromes often caused by inheritable gene mutations resulting in decreased telomere lengths. "Accordingly, Rtel1 is mutated in telomere syndromes, including severe DC56, 57, 58 and pulmonary fibrosis." (PMID 27033104, 2016). "TERC and TERT were initially the only genes tested in familial pulmonary fibrosis or telomere syndrome; other TRGs such as RTEL1 or PARN were later included in the NGS panel." (PMID 31796085, 2019).
Cirrhosis (2 papers, 2025). A chronic disorder of the liver in which liver tissue becomes scarred and is partially replaced by regenerative nodules and fibrotic tissue resulting in loss of liver function. "Older patients, many of whom had TERT and RTEL1 variants, were frequently affected by ILD or cirrhosis." (PMID 40179146, 2025). "Patient #6, a 64‐year‐old male with decompensated cirrhosis (LSM 26.6 kPa), portal hypertension and diabetes, was identified to have a rare variant (NM_001283009: p.D1017E) in RTEL1 gene and a suggested diagnosis of RTEL1‐associated telomerase syndrome was done." (PMID 39945383, 2025).
COVID-19 (2 papers, 2023). A disease caused by infection with severe acute respiratory syndrome coronavirus 2. "Here we demonstrate that up to 8.6% of severe COVID-19 patients bear RTEL1 ultra-rare variants, and show how this subgroup can be recognized." (PMID 37328761, 2023). "Several studies reported that both COVID-19 and RTEL1 variants are associated with shorter telomere length, but a direct association between the two is not generally acknowledged." (PMID 37328761, 2023). "RTEL1 variants are reportedly the first genetic risk factor for the prediction of lung impairment after COVID-19." (PMID 37328761, 2023). "Our RTEL1-mutated patients showed a higher prevalence of autoimmune COVID-19 comorbidities." (PMID 37328761, 2023). "In this paper, we demonstrated a relationship between RTEL1 genotype and COVID-19 phenotype, both in the acute and post-acute phase of the disease." (PMID 37328761, 2023). "Limited data are now available regarding telomere length and COVID-19 progression; RTEL1 variants, however, have never been investigated as a possible mechanistic connection between the two." (PMID 37328761, 2023). "This study aims to describe the clinical characteristics of an Italian cohort of COVID-19 patients, either bearing ultra-rare variants of RTEL1 or not." (PMID 37328761, 2023).
eczema (2 papers, 2021 to 2025). "We also found RTEL1 variant rs6062302 was significantly associated with immune system related traits such as dermatitis, eczema, Crohn’s disease, inflammatory bowel disease and allergic rhinitis." (PMID 39565278, 2025).
rheumatoid arthritis (2 papers, 2023 to 2025). A chronic, systemic autoimmune disorder characterized by inflammation in the synovial membranes and articular surfaces. "Using whole-exome sequencing, it was demonstrated that TERT, RTEL1, and PARN mutations occur in patients with rheumatoid arthritis-associated ILD at a 3-fold higher odds ratio than they do in a control population." (PMID 40095034, 2025).
anaplastic astrocytoma (1 paper, 2018). "Although the genotype distributions for SNPs were in accordance with HWE (P >.05), a novel missense variant (rs77086616, T434M) in RTEL1 was only observed in anaplastic astrocytoma and GBM patients (HWE P = 1.55x10-16)." (PMID 30462709, 2018).
autoimmune disease (1 paper, 2023). A disorder resulting from loss of function or tissue destruction of an organ or multiple organs, arising from humoral or cellular immune responses of the individual to their own tissue constituents. "However, RTEL1-mutated patients are more affected by autoimmune diseases (12% in mutated patients and 6% in WT patients) and hypertension (40% in mutated patients and 29% in WT patients) compared to other patients." (PMID 37328761, 2023). "Some of these patients also present autoimmune conditions, suggesting that, in heterozygous carriers of RTEL1 aberrations, fibrosis results from the combination of such monogenic defects with environmental factors and autoimmune diseases." (PMID 37328761, 2023).
B-cell lymphopenia (1 paper, 2017). "The progressive B-cell lymphopenia is a frequent observation in the context of impaired somatic recombination, thus we also examined V(D)J recombination in RTEL1-deficient fibroblasts of P1." (PMID 28507545, 2017).
cerebral cavernous malformation 2 (1 paper, 2021). "In addition, the harmonin homology domain (HHD) (or harmonin-N-terminal domain) from whirlin, harmonin, cerebral cavernous malformation 2 (CCM2), and regulator of telomere elongation helicase 1 (RTEL1) was assigned to the αα-hub domain group." (PMID 33361159, 2021).
chronic lung allograft dysfunction (1 paper, 2021). Chronic lung allograft dysfunction encompasses a range of pathologies that cause a transplanted lung to not achieve or maintain normal function. "Moreover, it has been found that IPF with mutations in TERT, RTEL1, or PARN has a significantly higher risk of death and chronic lung allograft dysfunction compared to those in patients without these mutations." (PMID 34859008, 2021).
colitis (1 paper, 2022). Inflammation of the colon. "To screen the potential and novel biomarkers of inflammation or colitis‐to‐carcinoma transition in humans, we identified three homeotic circRNAs of mmu_circ_0001109 (hsa_circ_0061166, hsa_circ_0061168 and hsa_circ_0092333) from the same host gene RTEL1." (PMID 35184406, 2022). "By RNA blasting between mice and humans, the RTEL1‐ and PRKAR2A‐derived circRNAs were identified, and the data showed that RTEL1‐derived circRNAs had no clinical significance in human colitis and CAC." (PMID 35184406, 2022).
developmental delay (1 paper, 2024). "As previously reported, depletion of RTEL-1 resulted in a developmental delay of the F1 generation." (PMID 38412290, 2024).
dysplastic nevi (1 paper, 2012). "Presence of dysplastic nevi was most strongly associated with the G allele of the SNP rs6011002 (OR = 3.30, 95% CI: 1.64, 6.61; P-trend = 7.75×10−4), which is located in the regulator of telomere elongation helicase 1 (RTEL1) gene region." (PMID 23300679, 2012).
epilepsy (1 paper, 2024). A brain disorder characterized by episodes of abnormally increased neuronal discharge resulting in transient episodes of sensory or motor neurological dysfunction, or psychic dysfunction. "Various solute carriers and transporters are associated with epilepsy, and the severity in Case 2 can be explained by an additional pathogenic variant in SLC22A17, a target gene that is likely to be modulated by RTEL1-TNFRSF6B overexpression via hsa-miR-3569-3p." (PMID 39156922, 2024). "In addition, RTEL1-TNFRSF6B and RTEL1 are located in the chromosomal region previously associated with epilepsy." (PMID 39156922, 2024). "Mutations in RTEL1 have previously been associated with telomere biology disorders but not epilepsy or PMEs." (PMID 39156922, 2024).
gastric adenocarcinoma (1 paper, 2016). "In this study, we found for the first time recurrent RTEL1 amplification statistically associated with advanced age and intestinal type of gastric adenocarcinoma." (PMID 27366209, 2016). "It is noteworthy to mention that we have chosen RTEL1 gene due to high frequency of its amplification in gastric adenocarcinoma samples observed by aCGH." (PMID 27366209, 2016).
hypersensitivity pneumonitis (1 paper, 2023). Hypersensitivity pneumonitis (HP) is a pulmonary disease with symptoms of dyspnea and cough resulting from the inhalation of an antigen to which the subject has been previously sensitized. "Two siblings (patients #5 and #8) presented the same variant in the RTEL1 gene but with different phenotypes: IPF and fibrotic hypersensitivity pneumonitis, respectively." (PMID 36833253, 2023).
ischemic stroke (1 paper, 2017). A stroke disorder caused by obstruction of blood flow to the brain, due to thrombotic (local blood clot formation) or embolic (due to a blood clot or other material traveling from another site) event. "To elucidate the association between LTL variation and ischemic stroke (IS) risk, we selected ten single nucleotide polymorphisms (SNPs) in three genes (TERC, TERT and RTEL1) that previously reported link to LTL, and genotyped SNPs of these genes in a case-control study." (PMID 28057933, 2017). "We then did Haplotype analysis to explore the connection between the TERT, RTEL1 haplotype and the risk of ischemic stroke, but no significant conclusion was found." (PMID 28057933, 2017).
Myelodysplasia (1 paper, 2025). Clonal hematopoietic stem cell disorders characterized by dysplasia (ineffective production) in one or more hematopoietic cell lineages, leading to anemia and cytopenia. "RTEL1 is involved in maintaining telomere length, and heterozygous loss‐of‐function RTEL1 variants have been associated with myelodysplasia and liver disease in adulthood." (PMID 39945383, 2025).
oral squamous cell carcinoma (1 paper, 2016). "Regarding oral squamous cell carcinoma, we observed 30 and 25 % of RTEL1 and ABCA13 amplification, respectively, but the presence of amplification was not statistically associated with clinicopathological data of patients." (PMID 27366209, 2016).